GNAS (GNAS complex locus)
Diseases named in the same sentence as GNAS in open-access papers (continued):
Sharing a sentence is not in itself a finding about the gene and the disease.
osteoporosis (2 papers, 2022 to 2025). A condition of reduced bone mass, with decreased cortical thickness and a decrease in the number and size of the trabeculae of cancellous bone (but normal chemical composition), resulting in increased fracture incidence. "A previous study reported that miR‐196a was poorly expressed when its direct downstream target GNAS was overexpressed in osteoporosis mice." (PMID 34918401, 2022).
pancreatitis (2 papers, 2023 to 2025). Inflammation of the pancreas. "A pathogenic variation in GNAS is suggestive for an IPMN and the interpretation of a pathogenic variant in KRAS remains somewhat challenging since this can be seen in in IPMNs, malignancies but also in pancreatitis." (PMID 36696439, 2023).
rectal adenocarcinoma (2 papers, 2022 to 2023). "Our analysis shows frequent mutations and amplifications of GNAS in TCGA COAD (colon adenocarcinoma), LIHC (liver hepatocellular carcinoma) and READ (rectum adenocarcinoma) cohorts." (PMID 35975235, 2022). "Most commonly gained or lost genes seen in rectal adenocarcinoma (FLT3, CDX2, GNAS, BCL2, SMAD4, MALT1) are not found in rectal squamous cell carcinoma." (PMID 36357817, 2023).
small cell lung carcinoma (2 papers, 2022 to 2023). Small cell lung cancer (SCLC) is a highly aggressive malignant neoplasm, accounting for 10-15% of lung cancer cases, characterized byrapid growth, and early metastasis. "Recently, it has been shown that GNAS promotes the development of small cell lung cancer via PKA." (PMID 35975235, 2022).
teratoma (2 papers, 2021 to 2024). A non-seminomatous germ cell tumor characterized by the presence of various tissues which correspond to the different germinal layers (endoderm, mesoderm, and ectoderm). "In the literature, molecular data show that KRAS and GNAS co-mutations are also present in primitive ovarian PMP associated with teratoma." (PMID 34930348, 2021).
thyroid (2 papers, 2022 to 2024). "These dogs could be developed as a disease model for research and translational medication trials for thyroid and possibly other tumour types, with somatic mutations in the GNAS gene." (PMID 36151521, 2022).
Thyroid adenoma (2 papers, 2020 to 2025). The presence of a adenoma of the thyroid gland. "EZH1 mutations are typically found in combination with TSHR or GNAS mutation and occur in approximately 30% hyperfunctioning thyroid adenomas." (PMID 41175860, 2025). "Other alterations include TSHR, GNAS, and EZH1 mutations in hyperfunctioning thyroid adenomas and wnt pathway dysregulation in cribriform morular carcinoma." (PMID 41175860, 2025).
thyroid nodule (2 papers, 2022 to 2024). A small circumscribed mass in the THYROID GLAND that can be of neoplastic growth or non-neoplastic abnormality. "In another study with 154 hot thyroid nodules, 10 samples capture mutations in the GNAS gene." (PMID 36151521, 2022).
tubular adenocarcinoma (2 papers, 2017 to 2020). An infiltrating adenocarcinoma in which the malignant cells form tubular structures. "The central role of GNAS mutations in CC was confirmed by other studies, that also provided significant data that GNAS and KRAS mutations are two different markers in CC and tubular carcinoma, respectively." (PMID 33266496, 2020).
tubular adenoma (2 papers, 2014 to 2024). A usually polypoid neoplasm arising from the glandular epithelium. "A higher proportion of GNAS mutations have been reported in tubulovillous and villous adenomas, but no GNAS mutations have been identified in tubular adenomas." (PMID 39309469, 2024). "Overall, we found GNAS codon 201 mutations in 46% (6/13) of villous adenomas and in 15% (3/20) of tubulovillous adenomas, and in no tubular adenomas." (PMID 24498230, 2014).
villous adenoma (2 papers, 2014 to 2024). An epithelial neoplasm morphologically characterized by the presence of a villous architectural pattern. "A recent study by Yamada and colleagues detected GNAS codon 201 hotspot mutations in 83% villous adenomas of the colon and rectum among Japanese patients." (PMID 24498230, 2014). "In five of these cases, the GNAS mutant cancers arose in a contiguous villous adenoma." (PMID 24498230, 2014).
viral infections (2 papers, 2021 to 2022). "The effect of the GNAS c.393C>T polymorphism on renal allograft outcome and posttransplant complications, such as viral infections, has not been previously explored." (PMID 36297195, 2022).
allergic asthma (1 paper, 2024). A asthma with a basis in a pathological type I hypersensitivity reaction. "Mice with dendritic cells deficient for GNAS result in a phenotype characterized by preferential Th2 differentiation, Th2 type inflammation, and subsequent development of allergic asthma." (PMID 38915393, 2024).
alopecia areata (1 paper, 2022). Loss of scalp and body hair involving microscopically inflammatory patchy areas. "Our results suggest that the association of genetically confirmed PHPT-1a and complete pseudo-anodontia associated with persistent patchy alopecia areata is a new additional nonclassical feature related to the GNAS pathogenic variant." (PMID 36553004, 2022).
Alzheimer disease (1 paper, 2021). A progressive, neurodegenerative disease characterized by loss of function and death of nerve cells in several areas of the brain leading to loss of cognitive function such as memory and language. "Given that G protein-coupled receptors (GPCRs) mediate the cellular response to most hormones/neurotransmitters, it is unsurprising that GPCR-related genes converge on normal aging (GNA15) and Alzheimer’s disease (GNAS, GNB5)." (PMID 34002691, 2021).
amoebiasis (1 paper, 2025). "Notably, infection-related pathways such as amoebiasis and Vibrio cholerae infection (e.g. GNAS, ACTG1 and HSPB1; adjusted P<0.01) were also identified." (PMID 40989927, 2025).
anaemia (1 paper, 2014). "Nevertheless, a number of marginal protective genotype associations were also observed between specific gene mutations and anaemia (CFTR, GNAS), hyperparasitaemia (DERL3, GBP7), hyperpyrexia (GBP7, ABO) and SMA (HbS, ADCY9)." (PMID 24934404, 2014).
Angelman syndrome (1 paper, 2012). A neurogenetic disorder characterized by severe intellectual deficit and distinct facial dysmorphic features. "At the GNAS locus loss of NESP RNA can cause autosomal dominant Pseudohypoparathyroidism type 1b (AD-PHP-Ib), while at the SNRPN-UBE3A locus a long ncRNA and processed snoRNAs play a role in Angelman-Syndrome (AS) and Prader–Willi-Syndrome (PWS)." (PMID 23226156, 2012).
appendix cancer (1 paper, 2017). "GNAS gene mutations are frequently found in a variety of malignancies, especially secretory tumors arising in exocrine and endocrine organs like mucinous colorectal and appendix cancers, suggesting oncogenic and secretory roles for this gene." (PMID 29290997, 2017).
asthenozoospermia (1 paper, 2021). "Some genes, such as FAM50B and GNAS, were reported to involve in the quality of sperm in asthenozoospermia through histone modification-type methylation." (PMID 34442404, 2021).
benign pancreatic tumors (1 paper, 2022). "Furthermore, the presence of GNAS and KRAS mutation in circulating ct-DNA can help to distinguish patients with premalignant IPMNs from benign pancreatic tumors." (PMID 35008381, 2022).
bladder adenocarcinoma (1 paper, 2025). "This novel approach has revealed that urachal adenocarcinoma is associated with specific gene mutations, including RAS, GNAS, SMAD4, and BRAF, which are absent in bladder adenocarcinoma." (PMID 39778497, 2025).
calcinosis cutis (1 paper, 2023). "Moreover, mutations in the GNAS gene have been previously associated with calcinosis cutis, a debilitating feature that can be present in SSc." (PMID 37270501, 2023).
cardiomyopathy (1 paper, 2019). A disease of the heart muscle or myocardium proper. "Similar gene expression patterns were observed in the cluster of cardiomyopathy genes (GNAs, MTHFR, CREBs, and FASN)." (PMID 30650650, 2019).
central osteosarcoma (1 paper, 2024). "Furthermore, low-grade central osteosarcoma (lgcOSA) is one of the most important differential diagnoses of FD, this study showed that only one lgcOSA case (1/15) had a GNAS mutation, which also indicates the ideal unique specificity of GNAS mutations in FD." (PMID 39135681, 2024).
cherubism (1 paper, 2012). Cherubism is a rare, self-limiting, fibro-osseous, genetic disease of childhood and adolescence characterized by varying degrees of progressive bilateral enlargement of the mandible and/or maxilla, with clinical repercussions in severe cases. "The investigators did not succeed in finding a mutation in GNAS or in the gene causing cherubism." (PMID 23230423, 2012).
Cirrhosis (1 paper, 2022). A chronic disorder of the liver in which liver tissue becomes scarred and is partially replaced by regenerative nodules and fibrotic tissue resulting in loss of liver function. "Further analysis showed that the frequency of autoantibody to GNAS started increasing in compensated cirrhosis patients (37.0%) with a jump in decompensated cirrhosis patients (53.2%) and reached a peak in early HCC patients (62.4%)." (PMID 35052777, 2022).
cocaine addiction (1 paper, 2021). "Among up- and downregulated genes from the pathway hsa05030:cocaine addiction are genes JUN, GNAS, BDFN, and CDK5R1 (upregulated), and FOSB, NFKB1, CREB1 and PPP1R1B (downregulated)." (PMID 34947877, 2021).
cognitive decline (1 paper, 2025). "Future prospective studies with larger cohorts, including age-matched controls and comprehensive neuropsychological testing, are needed to validate these preliminary findings and clarify the role of CCH and GNAS in cognitive decline." (PMID 41234936, 2025).
diffuse large B-cell lymphoma (1 paper, 2022). "A growth-repressive influence of Gαs on B cells is suggested by the finding of GNAS mutations in human diffuse large B cell lymphomas." (PMID 35639700, 2022).
endocrine tumors (1 paper, 2023). "Missense GNAS variants affecting residues R201 (namely p.R201C, p.R201S, and p.R201H), and G227 (p.G227R, p.G227L, and p.G227K) of GNAS have been described in endocrine tumors and other human neoplasms." (PMID 38067388, 2023).
folic acid deficiency (1 paper, 2017). "Our results confirm that periconceptional folate deficiency alters the methylation patterns of the maternal gDMRs in the GNAS imprinting cluster and influences the expression of genes under the control of these gDMRs." (PMID 29340017, 2017). "Overall, maternal folate deficiency seemed to have a more profound effect on methylation modification in the GNAS imprinting cluster compared to other two treated groups." (PMID 29340017, 2017). "In this study, we presented data demonstrating that GNAS imprinting was affected by both maternal and paternal folic acid deficiency." (PMID 29340017, 2017). "Taken together, by using ESCs cultured in FF medium, we demonstrated that folate deficiency could lead to aberrant GNAS imprinting and subsequently affect gene function through an altered chromatin structure." (PMID 29340017, 2017). "Furthermore, we investigated the effect of parental dietary folate deficiency on offspring development and GNAS imprinting regulation using a mouse model to validate the translational value of the observation from case studies." (PMID 29340017, 2017). "This supports the hypothesis that periconceptional folate deficiency increased the ratio of birth defects involving the impairment of imprinting establishment in the GNAS cluster." (PMID 29340017, 2017). "Taken together, data from this study suggest that folate deficiency in either parent may result in a disturbed GNAS imprinting before fertilization and continue through embryogenesis, leading to abnormal fetus development possibly through altering cAMP signaling." (PMID 29340017, 2017). "Data from studies on placentas gene expression in samples from pregnancies with IUGR have demonstrated down regulation of GNAS, however, there is no prior studies conducted to elucidate whether the GNAS imprinting cluster plays a role in periconceptional folate deficiency-related IUGR." (PMID 29340017, 2017).
Globozoospermia (1 paper, 2015). Any structural anomaly of the acrosome resulting in a round sperm head. "Six imprinted genes showed different 5hmC patterns between normal and abnormal sperm (GDAP1L1, GNAS, KCNK9, LIN28B, RB1, RTL1), and five imprinted genes showed different 5hmC patterns between normal and globozoospermia sperm (KCNK9, LIN28B, RB1, SLC22A18, ZDBF2)." (PMID 25762640, 2015).
glycogen storage disease (1 paper, 2015). "Of note, H-HCA do not occur in patients with glycogen storage disease (GSD), neither are they associated with CTNNB1, IL6ST, GNAS, and STAT3 mutations." (PMID 26404250, 2015).
goblet cell adenocarcinomas (1 paper, 2023). "With reduced frequency, mutations in the GNAS gene also occur in appendiceal adenocarcinomas, signet ring cell adenocarcinomas of the appendix, and appendiceal goblet cell adenocarcinomas." (PMID 37509254, 2023).
gout (1 paper, 2022). A condition characterized by painful swelling of the joints, which is caused by deposition of urate crystals. "GNAS variants predispose patients to an abnormal synovial environment and the deposition of uric acid crystals, promoting the formation of gout and related osteoarthritis." (PMID 35813212, 2022).
growth retardation (1 paper, 2020). "Transcripts from GNAS complex locus, on the other side, are involved in different signal transduction pathways and a variety of cellular responses, having being also associated with intrauterine growth retardation and thus small size for gestational age." (PMID 32393379, 2020).
H.pylori (1 paper, 2021). "Depending on our previous genome-wide methylation profiles prior to and after anti-H.pylori treatment, the present study further validated that GNAS and MTERF1 methylation levels in blood leukocyte and gastric mucosa are correlated, and may be affected by H.pylori infection." (PMID 35003353, 2021).
Hearing impairment (1 paper, 2025). A decreased magnitude of the sensory perception of sound. "Although its role in ototoxicity is not fully understood, postzygotic activating mutations in GNAS (20q13.3) have been linked to hearing impairments." (PMID 41009448, 2025).
hepatobiliary tumors (1 paper, 2021). "Analyses of public data revealed somatic GNAS alterations in 2.1% hepatobiliary tumors and relation with parasite infection." (PMID 33832503, 2021).
hepatocellular adenoma (1 paper, 2025). A benign epithelial neoplasm arising from the hepatocytes. "The association of MAS and hepatocellular adenoma could potentially be explained by STAT3 The association of MAS and hepatocellular adenoma could potentially be explained by STAT3 (inflammatory pathway) activation induced by GNAS activation activation induced by GNAS activation." (PMID 40078582, 2025).
Hypercalciuria (1 paper, 2024). "Thus, the hypercalciuria is a consequence of the TRPV5 mutation, but not the GNAS mutation, in the proband." (PMID 38528055, 2024).
hyperopia (1 paper, 2022). A refractive error in which rays of light entering the eye parallel to the optic axis are brought to a focus behind the retina, as a result of the eyeball being too short from front to back. "Also, a GNAS gene was associated with HM, TRAM1, CTNNB1, TENM3 and RUNX with myopia and/or refractive error, and EIF4B with low myopia/hyperopia in Europeans." (PMID 36685896, 2022).
hyperplastic polyp (1 paper, 2026). A polyp found mainly in the stomach and colon. "Collectively, these findings support the diagnosis of a gastric foveolar‐type hyperplastic polyp of the duodenum harboring GNAS and KRAS mutations." (PMID 40964650, 2026). "Herein, we report a duodenal gastric foveolar‐type hyperplastic polyp with GNAS and KRAS mutations, highlighting the importance of histopathological and molecular evaluation even in lesions without cytological dysplasia." (PMID 40964650, 2026). "We report a gastric foveolar‐type hyperplastic polyp of the duodenum harboring mutations in the GNAS and KRAS genes." (PMID 40964650, 2026). "Based on these findings, the final diagnosis was a gastric foveolar‐type hyperplastic polyp harboring GNAS and KRAS mutations." (PMID 40964650, 2026).
insomnia (1 paper, 2023). A sleep disorder characterized by difficulty in falling asleep and/or remaining asleep. "Furthermore, a UK Biobank GWAS study of 113,000 individuals with insomnia identified GNAS as a potential gene candidate in females." (PMID 37697338, 2023).
intestinal tumor (1 paper, 2017). "GNAS R201C was found to cause augmentation of both the Wnt and ERK1/2 MAPK pathways in the intestinal epithelium of mice and the mutation co-operated with inactivation of Apc in intestinal tumor formation in vivo." (PMID 28160572, 2017).
intracystic papillary neoplasms (1 paper, 2013). "So, it is natural that the status of GNAS mutations is different between perihilar IPNBs and intracystic papillary neoplasms in gallbladder." (PMID 24312577, 2013).
liver cirrhosis (1 paper, 2022). "Based on Kojiro’s discovery, it was speculated that the increased autoantibody to GNAS in patients with liver cirrhosis might be due to the undetectable early HCC patients occupying a certain proportion." (PMID 35052777, 2022).
liver fibrosis (1 paper, 2025). "In a CCl4-induced liver fibrosis model, Que-BMSC-EVs inhibited M1-type macrophage polarization and alleviated liver inflammation by suppressing the GNAS/PI3K/ERK/STAT3 signaling pathway." (PMID 40852596, 2025).
Lynch syndrome (1 paper, 2023). An autosomal dominant hereditary neoplastic syndrome characterized by the development of colorectal carcinoma and a high risk of developing endometrial carcinoma, gastric carcinoma, ovarian carcinoma, renal pelvis carcinoma, and small intestinal carcinoma. "Additionally, a previous report has showed a GNAS mutation in a Lynch syndrome-associated ASC." (PMID 36790480, 2023).
mucinous lung adenocarcinomas (1 paper, 2020). "Based on the clinicopathology analysis and sequencing of oncogenes, mutations in GNAS along with Ras/Raf pathway tend to occur in invasive mucinous lung adenocarcinomas." (PMID 32628820, 2020).
mucinous ovarian carcinomas (1 paper, 2021). An invasive malignant neoplasm that arises from the ovary and is characterized by the presence of malignant epithelial cells that contain intracytoplasmic mucin and may resemble the epithelial cells of the endocervix or gastrointestinal tract. "Molecular data on primitive mucinous ovarian carcinomas without the context of PMP showed frequent mutations in KRAS, without GNAS mutation." (PMID 34930348, 2021).
mucopolysaccharidosis (1 paper, 2022). A group of autosomal recessive or X-linked inherited lysosomal storage disorders affecting the metabolism of mucopolysaccharides, resulting in the accumulation of mucopolysaccharides in the body. "Genetic testing included CMA, Prader-Willi methylation, mucopolysaccharidosis biochemical testing, and GNAS and WFS1 sequencing." (PMID 35362483, 2022).
multiple sclerosis (1 paper, 2019). A progressive autoimmune disorder affecting the central nervous system resulting in demyelination. "Importantly, altered allelic expression of two imprinted genes (ZNF331 and GNAS) and five non-imprinted genes (ABLIM1, UBE2I, KIAA1267, CD6, and ATHL1) were detected between the multiple sclerosis discordant co-twins." (PMID 31850058, 2019).
myopia (1 paper, 2022). "Several targets of these miRNAs, e.g. GNAS, TRAM1, CTNNB1, EIF4B, TENM3 and RUNX were previously associated with myopia/HM/refractive error in Europeans in genome-wide association studies." (PMID 36685896, 2022).